IL27 (interleukin 27)
Diseases named in the same sentence as IL27 in open-access papers (continued):
Sharing a sentence is not in itself a finding about the gene and the disease.
ovarian carcinoma (11 papers, 2015 to 2021). A malignant neoplasm originating from the surface ovarian epithelium. "IL-27 increases CD39 expression in ovarian cancer associated macrophages." (PMID 34234781, 2021). "Here, the depletion of IL-27 attenuated the expression of PD-L1 and IL-10 in macrophages isolated from ovarian cancer patients." (PMID 33418929, 2021). "IL-27 has recently also been shown to increase IL-18bp in skin resident cells and in human ovarian cancer cells." (PMID 34663245, 2021). "IL-27 also reduced the proliferation of human ovarian cancer cells by activating STAT3 and inhibiting Akt signaling pathways." (PMID 33418929, 2021). "In this report, we show for the first time that the leaderless protein GBP1 is released by IL-27- or IFN-γ-stimulated ovarian cancer cells in vitro, whereas other members of the GBP family are induced intracellularly but not secreted." (PMID 32093058, 2020). "For example, the use of IL-15 can enhance NK cell cytotoxic function against ovarian cancer and IL-27 has been shown to enhance IL-15 mediated NK cell activation." (PMID 31681561, 2019). "A recent proteomic analysis on human ovarian cancer cell lines revealed that IL-27 and IFN-γ shared a broad set of activities, such as the HLA class I antigen presentation." (PMID 31221207, 2019). "Altogether, these data suggested a possible immune-regulatory role of endogenous IL-27 in ovarian cancer." (PMID 28255204, 2017). "We initially chose the SKOV3 ovarian cancer cell line, which has been widely utilized as a serous ovarian adenocarcinoma cell model, and responds to IL-27 stimulation by up-regulating the expression of immune regulatory IL-18BP, IDO, and PD-L1 molecules." (PMID 27683036, 2016). "It is of note that immunohistochemical analysis of human ovarian cancer specimen revealed that IL-27-producing leukocytes are also present in some tumor microvessels." (PMID 26657115, 2015). "We reported that IL-27 induces the expression of the IL-18 inhibitor IL-18BP, in human Epithelial Ovarian Cancer (EOC) cells, thus potentially limiting the immune response." (PMID 26657115, 2015). "Moreover, IL-27 signaling in human ovarian cancer cells activated STAT1/STAT3 and induced the constitutive expression of IDO." (PMID 33418929, 2021). "This hypothesis was recently confirmed by a proteomic analysis of IFN-γ or IL-27-treated ovarian cancer cells, which showed that 82.2% of modulated proteins were concordantly regulated by the two cytokines." (PMID 28255204, 2017). "However, our recent data showed that, beyond these anti-tumor effects, IL-27 also induces the expression of immune regulatory molecules such as IL-18BP, the natural inhibitor of the Th1-inducing cytokine IL-18, in ovarian cancer cells." (PMID 27683036, 2016). "Since several of the commonly up-regulated proteins have been involved in anti-proliferative or pro-apoptotic effects of IFN-γ, we investigated whether IL-27 shares these functions on ovarian cancer cell lines." (PMID 27683036, 2016). "Indeed, IL-27 significantly enhanced total HLA class I molecules detected by W6/32 mAb on 5 out of 6 ovarian cancer cell lines." (PMID 27683036, 2016). "Interestingly, similar findings were also reported in a most recent publication describing an IL-27 dependent induction of CD39 on macrophages in ovarian cancer patients." (PMID 27532024, 2016). "In addition, IL-27 can also up-regulate surface HLA class I levels in different types of human cancer cells already displaying these molecules, including ovarian cancers and NSCLC." (PMID 27683036, 2016). "In addition, others have shown synergistic effect of IL-27 with IL-18 in NK cells and IL-27 dependent up-regulation of IL-18bp in human ovarian cancer cells and skin resident cells, suggesting some interactions between IL-27 and IL-18 during inflammation and immune responses." (PMID 34663245, 2021).
ovarian carcinoma (continued). "Also, IL-27 mediated IDO and PD-L1 expression in ovarian cancer cells, suggesting that the effect of IL-27 and IFN-γ may show a broader overlap." (PMID 28255204, 2017). "IL-27 induces the expression of immune-regulatory molecules such as PD-L1 and IDO in human ovarian cancer cells." (PMID 34234781, 2021). "To identify novel extracellular mediators, potentially involved in epithelial ovarian cancer (EOC) biology, we analyzed the effect of IL-27 or IFN-γ on the secretome of cultured EOC cells by mass-spectrometry (nano-UHPLC-MS/MS)." (PMID 32093058, 2020). "We previously showed that IL-27, similar to IFN-γ, upregulated the expression of IL-18BP, a natural inhibitor of IL-18 activity, in ovarian cancer cells, and that IL-18BP protein accumulates in the ascites of patients." (PMID 28255204, 2017). "Here we show that one out of 6 ovarian cancer cell lines had an IFN-γ- and IL-27-resistant HLA-null phenotype, due to the same defect of the B2M gene." (PMID 27683036, 2016). "A similar analysis was performed in another IL-27-responsive ovarian cancer cell line named OC316, which showed a similar pattern of proteins, commonly modulated by IL-27 and IFN-γ." (PMID 27683036, 2016). "To better dissect the effects of IL-27 and IFN-γ on ovarian cancer cells, we used a proteomic approach to identify the profile of cytokine-regulated proteins." (PMID 27683036, 2016). "Here, a proteomic analysis reveals that IL-27 and IFN-γ display a broad overlap of functions on human ovarian cancer cells." (PMID 27683036, 2016). "We found that IL-27, a cytokine of the IL-12 family, produced by myelomonocytic cells, shares several effects with IFN-γ such as the induction of IDO1, PD-L1, and IL-18BP, in human epithelial ovarian cancer (EOC) cells." (PMID 32093058, 2020). "Similarly, IL-27 was found to induce the expression of immune-regulatory molecules such as IL-18BP, the natural inhibitor of IL-18, and PD-L1 and IDO in human ovarian cancer cells and also in other cancer cells in vitro." (PMID 28255204, 2017). "Indeed, IL-27 reduced cell proliferation, as detected by MTT, increased the apoptotic cell rate, and inhibited cell migration of ovarian cancer cell lines in vitro." (PMID 27683036, 2016). "Nontheless, the assessment of the real role of IL-27 in ovarian cancer biology would require further studies in suitable syngeneic models." (PMID 26657115, 2015).
Pleural effusion (11 papers, 2012 to 2022). The presence of an excessive amount of fluid in the pleural cavity. "IL-27 in pleural fluid is a sensitive and specific biomarker for the differential diagnosing tuberculous pleural effusion from pleural effusions with the other causes." (PMID 22792330, 2012). "The objective of the present study was to investigate the presence of interleukin (IL)-27 in pleural effusions and to evaluate the diagnostic significance of pleural IL-27." (PMID 22792330, 2012). "Moreover, TB pleural effusions also exhibit increased amounts of IL-27, pointing at a potential usage of the cytokine as a biomarker to differentiate between TB pleural effusions and other causes of pleural effusions." (PMID 35116036, 2021). "Thus, the diagnostic accuracy of IL-27 levels in pleural effusion was 97.72% (86/88)." (PMID 33436672, 2021). "Thus, the diagnostic accuracy of IL-27.ADA levels in pleural effusion was 98.86% (87/88)." (PMID 33436672, 2021). "Sources of IL-27 in TB pleural effusions appear to be monocytes, MΦ, B cells, both CD4+ and CD8+ T cells, NK/NKT cells as well as mesothelial cells." (PMID 35116036, 2021). "IL-27 production in TB pleural effusion has been ascribed to various cellular sources including CD4+ and CD8+ T cells, B cells, NK/NKT cells, monocytes/macrophages and mesothelial cells." (PMID 33334075, 2020). "Both subunits of the heterodimeric cytokine are expressed in human TB granuloma and in TB pleural effusion, the latter providing the potential to use IL-27 levels as a specific biomarker for the differential diagnosis of tuberculous pleurisy." (PMID 33334075, 2020). "Pleural fluid levels of ADA, INF-γ, and IL-27 are present in significantly higher concentrations in patients with TPE than those in patients with other types of pleural effusion." (PMID 31455239, 2019). "The concentrations of IL-27 were determined in pleural fluids and sera from 68 patients with tuberculous pleural effusion, 63 malignant pleural effusion, 22 infectious pleural effusion, and 21 transudative pleural effusion." (PMID 22792330, 2012). "Two hundred seventy-four consecutive adult patients with pleural effusion were selected from Beijing and Wuhan between January 1, 2014 and June 30, 2015, and their pleural fluid concentrations of ADA, IFN-γ, and IL-27 were tested." (PMID 32571326, 2020). "In four of these patients, interleukin (IL)-23, IL-27, and interferon-gamma (IFN-γ) measurements were not performed since pleural effusion samples could not be collected because the effusion had been drained prior to the study." (PMID 31455239, 2019).
Allergy (10 papers, 2015 to 2025). An allergy is an immune response or reaction to substances that are usually not harmful. "Given its immunoregulatory properties, IL-27 has been considered a potential therapeutic target for Th2-mediated allergic diseases." (PMID 39735535, 2024). "Understanding the biology of IL-27 in more detail and revealing the context that determines the outcome are important for applying IL-27 for therapeutic use in various diseases, such as autoimmune disorders, infection, allergies, and cancer." (PMID 25633106, 2015). "Similar to the observations in the allergy model, a significant reduction in the percentage of Tbet+ Th1 cells in the spleen, and the production of Th1-mediated cytokines, such as IFN-γ, IL-12p70 and IL-27 were observed in these animals." (PMID 34975906, 2021). "Fifth, the influence of IL-4 combined with other genes (such as IL-6, IL-10, IL-17, IL-27, IFN-γ, etc.)or the environments on allergies has not been analyzed." (PMID 33834211, 2021).
ZIKV infection (10 papers, 2017 to 2025). "Collectively, these data indicate that IL-27 signaling is required to prevent fetal pathology and can restrict viral replication in placental tissues during congenital ZIKV infection." (PMID 40502752, 2025). "Using a primary human trophoblast organoid model, we found that IL-27 signaling machinery is expressed by fetal trophoblasts, and that IL-27 is capable of restricting ZIKV infection of trophoblasts similarly to IFNλ." (PMID 40502752, 2025). "Together, these findings establish IL-27 as an innate antiviral defense at the maternal-fetal interface and highlight its potential for combating congenital ZIKV infections and supporting healthy fetal outcomes." (PMID 40502752, 2025). "(2020) showed that subcutaneous administration of IL-27 reduced mortality and the onset of neurological symptoms of ZIKV infection in an IFN-independent manner." (PMID 38720890, 2024). "Generation of innate AVPs, including OAS1, OAS2, OASL, and MX1, in response to IL27 was found to be protective against Zika virus infection in human keratinocytes." (PMID 37310504, 2023). "We next sought to determine whether IL-27 signaling regulates congenital ZIKV infection in trophoblasts." (PMID 40502752, 2025). "We observed significantly higher ZIKV burdens in the combined fetal/placental tissues from IL27RA−/− dams, suggesting that IL-27 may play a role in limiting ZIKV infection at the maternal-fetal interface." (PMID 40502752, 2025). "Finally, we show that IL-27 signaling is critical within the context of congenital murine ZIKV infection, as IL-27 restricts placental ZIKV burdens and protects against pathologic fetal outcomes early in gestation." (PMID 40502752, 2025). "Thus, the role of IL-27 in regulating immune cell activity specifically during congenital ZIKV infection warrants further investigation." (PMID 40502752, 2025). "Finally, we show that IL-27 signaling is critical within the context of congenital murine ZIKV infection, as IL-27 restricts placental ZIKV burdens and is protective against pathologic fetal outcomes." (PMID 40502752, 2025). "IL-27 works in concert with type I IFN in inhibiting Zika virus infection." (PMID 37725438, 2023). "Indeed, IL-27-induced antiviral proteins are functional, as IL-27 treatment substantially suppresses Zika virus infection in human keratinocytes." (PMID 34045653, 2021). "We observed increased tissue pathology in the fetuses of IL-27 deficient dams during congenital ZIKV infection, but not in the fetuses of IL-27-deficient dams treated with HMW poly(I:C); however, these experiments did not explore the possibility of IL-27 regulating immune cell-mediated pathology." (PMID 40502752, 2025). "In our murine model of congenital ZIKV infection, we observed that IL-27 signaling restricted placental ZIKV burdens and was protective against pathologic fetal outcomes indicating that IL-27 was critical to infection at gestational day E6.5." (PMID 40502752, 2025). "IPA also predicted many cytokines, including IL-15, IL-27, IL-32, C5, IL-18, and EB13, were significantly up-regulated by ZIKV infection in HSerC." (PMID 32511241, 2020). "However, there was a significantly greater incidence of resorption in the fetuses of IL-27-neutralized (28% total resorption; 8% early resorption) and IL27RA−/− (23.1% total resorption; 5.1% early resorption) dams during congenital ZIKV infection." (PMID 40502752, 2025).
chronic obstructive pulmonary disease (9 papers, 2012 to 2022). A chronic and progressive lung disorder characterized by the loss of elasticity of the bronchial tree and the air sacs, destruction of the air sacs wall, thickening of the bronchial wall, and mucous accumulation in the bronchial tree. "Function of IL-27 was related to the pathogenesis of chronic obstructive pulmonary disease (COPD) and patients with pulmonary TB." (PMID 22570668, 2012). "Human pulmonary cDC2s mediated IL-10 producing Treg, which suppressed chronic obstructive pulmonary disease (COPD), via IL-10, IL-27 and inducible T cell costimulator ligand (ICOSL)." (PMID 31640263, 2019).
co-infection (9 papers, 2014 to 2024). "In PWH and CMV coinfection, IL-27 plasma levels were negatively correlated with viral load and positively associated with CD4 T cell counts suggesting a beneficial effect in CD4 T cell reconstitution in CMV infected PWH." (PMID 38966644, 2024). "We recently reported that in HIV-M. tuberculosis co-infection, IL-27 is expressed by myeloid-derived suppressor cells with diminished MyD88 gene expression." (PMID 36863206, 2023). "We recently reported that neutralizing IL-27 controls replication of M. tuberculosis in the settings of HIV-M. tuberculosis co-infection." (PMID 36863206, 2023). "We have previously shown that IL-27 inhibits the anti-M. tuberculosis activity in the settings of HIV-M. tuberculosis co-infection." (PMID 36863206, 2023). "In this study, we provide the first evidence of the direct effect of IL-27 on M tuberculosis in HIV- M tuberculosis co-infection." (PMID 33995365, 2021). "Our data suggest that IL-27 is regulated during falciparum malaria independently of co-infection with HIV mediating both inflammatory and anti-inflammatory effects, potentially playing an immune-regulatory role during falciparum malaria." (PMID 31964363, 2020). "To test this, we utilized IL-27 receptor α knock-out (IL-27Rα−/−) mice and examined the impact of the IL-27 signaling on viral, bacterial and co-infection pathogenesis." (PMID 25651926, 2015). "IL-27 is known to inhibit Type 17 immunity, suggesting a potential critical role for IL-27 in viral and bacterial co-infection." (PMID 25651926, 2015). "Interleukin-27 (IL-27), a cytokine which inhibits HIV and HCV replication in vitro, associates with HIV infection and HIV/HCV co-infection in clinical settings." (PMID 24816922, 2014). "In one previous study the suppression of IL-27 by HCV co-infection was observed, yet the study was conducted in different conditions with patients receiving HAART and the sample size was only nine." (PMID 24816922, 2014). "Moreover, in PWH and CMV coinfection, in vitro stimulation of PBMCs with CMVpp65 in the presence of IL-27 stimulation led to increased IFNγ secretion by CMVpp65-specific CD4 T cells in both CMV+PWH and CMV+PWOH (People Without HIV)." (PMID 38966644, 2024). "Further, IL-27 may play a dual role in co-infection immunopathology; limiting inflammation and tissue injury, while increasing susceptibility to secondary bacterial pneumonia." (PMID 25651926, 2015). "This study suggests a potential role for IL-27 signaling during viral and bacterial co-infection." (PMID 25651926, 2015). "In this study, we aim to explore how the co-infection of the HIV and HCV virus affects serum IL-27 titer among treatment-naïve subjects." (PMID 24816922, 2014). "Our findings show that HCV co-infection altered the correlations between HIV viral loads, IL-27 titers and CD4+ T cell counts." (PMID 24816922, 2014). "It was reported that IL-27 was negatively correlated with HIV viral load, downregulated under HCV co-infection, and related to the CD4+ T cell counts." (PMID 24816922, 2014). "In conclusion, our results suggest that IL-27 differs in treatment-naïve groups which have HIV mono-infections and HIV/HCV co-infections." (PMID 24816922, 2014). "However, in the HCV-co-infected group, the level of CD4+ negatively associated to IL-27, thereby meaning that under the HCV co-infection, the anti-HIV feedback arc set might be interrupted, which might result in the uncontrolled or less effective suppression of HIV replication." (PMID 24816922, 2014). "We are currently investigating the mechanism of IL-27 mediated suppression of innate immunity in response to M tuberculosis with or without co-infection with HIV." (PMID 33995365, 2021). "Importantly, in this study, we provide the first evidence of IL-27 mediated regulation of IFNγ and IL-10 during human CMV infection in the setting of HIV co-infection." (PMID 28338007, 2017).
co-infection (continued). "Overall, our results suggest that IL-27 differs in treatment-naïve groups with HIV mono-infections and HIV/HCV co-infections, thereby providing critical information to be considered when caring and treating those with HIV mono-infection and HIV/HCV co-infection." (PMID 24816922, 2014). "Because IL-27 actives naïve CD4+ T-cells, this difference implies that co-infection with HCV might have altered the expression profile of IL-27, disrupted the biological function of IL-27, or accelerated CD4+ T cell death." (PMID 24816922, 2014). "This is, however, the first report of IL-27 levels in adult patients with falciparum malaria demonstrating increased plasma levels as compared with healthy controls and HIV-infected patients with similar febrile illness, independent of co-infection with HIV." (PMID 31964363, 2020). "In addition, we show that IL-27 controls IFNγ and mediates IL-10 producing Tr1 cells during CMV infection, with or without co-infection with HIV." (PMID 28338007, 2017).